PCK2 (phosphoenolpyruvate carboxykinase 2, mitochondrial)
Diseases named in the same sentence as PCK2 in open-access papers (continued):
Sharing a sentence is not in itself a finding about the gene and the disease.
lung adenocarcinoma (4 papers, 2020 to 2023). A carcinoma that arises from the lung and is characterized by the presence of malignant glandular epithelial cells. "In lung adenocarcinoma, PCK2 expression was associated with significantly improved overall survival, while the opposite was found for GLUT1." (PMID 32777161, 2020). "We found that PCK2 was preferentially expressed in the lung adenocarcinoma subtype, while GLUT1 expression was higher in squamous cell carcinoma." (PMID 32777161, 2020). "Although PCK2 also appeared to have an oncogenic function in-vitro, we decided to focus on PCK1 because it was enriched by TCGA geneset analysis and had prognostic significance in lung adenocarcinoma, while PCK2 did not." (PMID 37407566, 2023). "Additionally, we found increased protein expression of ATF4 and PHGDH, along with upregulated mRNA levels of PCK2, PHGDH, PSAT1, and PSPH, in DNM1L‐KO lung adenocarcinoma cell lines." (PMID 33152171, 2021).
breast tumors (3 papers, 2022 to 2023). "Intriguingly, PCK2 participates in the regulation of basal-like breast tumor stemness and OXPHOS." (PMID 37250903, 2023).
glioblastoma (3 papers, 2017 to 2025). The most malignant astrocytic tumor (WHO grade IV). "To further investigate the correlation between PCK2 and different immune cells, as well as the association between immune cell infiltration and glioblastoma prognosis, we conducted an analysis using the CIBERSORT based TIMER web tool." (PMID 39744481, 2025). "Taking together, PCK2 is strongly associated with mesenchymal glioblastoma and can serve as a potential biomarker for this subtype." (PMID 39744481, 2025). "In conclusion, our study sheds light on the multifaceted role of PCK2 in glioblastoma, encompassing both its prognostic significance and its potential influence on immune modulation." (PMID 39744481, 2025). "Our study sheds light on the multifaceted role of PCK2 in glioblastoma, unraveling its significance as a poor prognostic factor and its strong associations with immune cell infiltration, particularly tumor associated dendritic cells." (PMID 39744481, 2025). "Despite the growing interest in PCK2 as a potential biomarker and its links to tumor immunology, research on its relevance in glioblastoma is still poorly defined." (PMID 39744481, 2025). "The findings demonstrated that glioblastoma patients with high PCK2 expression showed substantial enrichment in various immune response pathways, including Toll-like, JAK, NOD-like, RIG, and Fc epsilon RI signaling." (PMID 39744481, 2025). "PCK2 is preferentially expressed in mesenchymal subtype and correlates with immune infiltrates and immunosuppression in glioblastoma." (PMID 39744481, 2025). "The results revealed that high expression of PCK2 in glioblastoma indicates a higher proportion of infiltrating T reg cells, natural killer cells, myeloid-derived suppressor cells (MDSCs), CD8+ T cells, dendritic cells, and macrophages." (PMID 39744481, 2025). "In IDH1MUT glioma, PC levels were markedly higher than in IDH1WT glioma, whereas PCK2 expression levels were significantly lower in IDH1MUT glioma although differences in PCK2 levels between IDH1WT and IDH1MUT in glioblastoma were less apparent." (PMID 28467784, 2017).
kidney cancer (3 papers, 2020 to 2023). Primary or metastatic malignant neoplasm involving the kidney. "This experiment analyzed the expression of PCK2 in kidney cancer tissues and cell lines, and found that the expression of PCK2 is down-regulated." (PMID 32699530, 2020). "Kidney cancer patient with SUCLG1, GLDC, SLC12A1, PCK2, ATP1A1 and PDHA1 alteration showed highest mortality." (PMID 32699530, 2020). "Therefore, UCLG1, PCK2, GLDC, have the potential to be a novel and valuable oncotarget protein for human kidney cancer." (PMID 32699530, 2020). "However, the function of PCK2 has not been investigated in kidney cancer." (PMID 32699530, 2020).
primary angle-closure glaucoma (3 papers, 2021 to 2025). An angle-closure glaucoma characterized by closure of the anterior chamber angle by an intrinsic defect such that aqueous outflow is blocked and the intraocular pressure becomes inappropriately elevated leading to optic nerve damage and visual field loss. "Further, a heterozygous mis-sense variant (c.977C>T; p.P326L) in PCK2 was found in a Chinese family, causing primary angle-closure glaucoma." (PMID 40428427, 2025). "It has been suggested that PCK2 gene mutation causes primary angle-closure glaucoma (PACG) by disrupting the AKT/GSK3α signaling pathway." (PMID 38890507, 2024).
COVID-19 (2 papers, 2023 to 2024). A disease caused by infection with severe acute respiratory syndrome coronavirus 2. "These proteins either act as positive regulators of cell death (HBG1, HBB, HBD, and HBA1) or are involved in the cellular response to tumor necrosis factor (FABP4, GPD1, THBS1, ASS1, and PCK2), suggesting that apoptosis may be an important cause of heart failure in patients with COVID-19." (PMID 38087340, 2023).
glioma (2 papers, 2017 to 2025). A benign or malignant brain and spinal cord tumor that arises from glial cells (astrocytes, oligodendrocytes, ependymal cells). "The mRNA expression level of PCK2 was investigated in glioma samples retrieved from the CGGA and TCGA databases." (PMID 39744481, 2025). "Additionally, the examination of different glioma grades demonstrated that PCK2 expression generally increases with tumor grade, suggesting a positive correlation between PCK2 levels and glioma progression (One-way ANOVA, P<0.05)." (PMID 39744481, 2025). "Furthermore, these findings were validated in nine human glioma tissues at the protein level through immunohistochemistry staining, as compared to lower grade gliomas (grade 2 and 3), PCK2 is significantly highly expressed in GBM patients." (PMID 39744481, 2025). "Immunohistochemistry was used to detect PCK2 expression in glioma samples." (PMID 39744481, 2025). "Here, we show that PCK2 is increasingly expressed in GBM tissues and could serve as poor prognostic indicator for glioma patients." (PMID 39744481, 2025). "GSEA analysis demonstrates a positive correlation between high PCK2 expression and the gene set of the mesenchymal subtype signature in glioma patients, while a negative correlation with the proneural signature." (PMID 39744481, 2025).
glycogen metabolism disorders (2 papers, 2022 to 2025). "Diseases associated with PCK2 include phosphoenolpyruvate carboxykinase deficiency and glycogen storage diseases, the latter of which has been associated with lens opacity." (PMID 40428427, 2025).
ovarian carcinoma (2 papers, 2022 to 2025). A malignant neoplasm originating from the surface ovarian epithelium. "The clinical relationship between NAC1 and its potential downstream target, phosphoenolpyruvate carboxykinase isoform 2 (PCK2), was examined using immunohistochemical analysis of ovarian cancer specimens." (PMID 41096648, 2025). "In addition, through the literature review, we found that except CYBB, VDAC2, IDH1, MT1G, SLC1A4, PCK2, SLC3A2, the prognostic value of other FRGs in ovarian cancer has been reported, which provided a possibility for constructing a prognostic model." (PMID 36386203, 2022).
renal carcinoma (2 papers, 2020 to 2025). A carcinoma arising from the epithelium of the renal parenchyma or the renal pelvis. "In conclusion, the experimental results showed that over expression of SUCLG1, PCK2, and GLDC can inhibit the progression of renal cancer cells." (PMID 32699530, 2020). "In order to clarify the mechanisms of SUCLG1, PCK2, and GLDC in renal cancer, this study further focused on their proliferation, migration, invasion, and cell cycle of renal cancer cells through cell biology experiments." (PMID 32699530, 2020). "In this study, we analyzed the databases of GEO, TCGA, GEPIA, Oncomine, and found that six genes (SUCLG1, PCK2, GLDC, SLC12A1, ATP1A1, and PDHA1), are related to the survival prognosis of patients with renal cancer." (PMID 32699530, 2020). "In order to clarify the molecular mechanism of these genes, we selected 3 molecules (SUCLG1, PCK2, GLDC) that have not previously been studied in renal cancer, and conducted in vitro experiments on them." (PMID 32699530, 2020).
atherosclerosis (1 paper, 2022). A disease characterized by the build-up of fatty material and calcium deposition in the arterial wall resulting in partial or complete occlusion of the arterial lumen. "Targeting PCK2, a downstream signaling mediator of VSMC proliferation, may be a novel therapeutic approach to modulate VSMC proliferation in atherosclerosis." (PMID 35982907, 2022).
bone metabolic disorders (1 paper, 2022). "This metformin-PCK2-mediated signaling pathway could therefore be a novel mechanism for mitigating craniofacial malformation and osteoporosis, which thus opens up a new avenue for clinical treatment strategies for bone metabolic disorders." (PMID 36376276, 2022).
brain infarction (1 paper, 2022). Tissue necrosis in any area of the brain, including the cerebral hemispheres, the cerebellum, and the brain stem. "PH reduced brain infarction, neurological deficits, protein levels of glycolytic enzymes (GLUT-1, GLUT-3, PFK and LDH), gluconeogenic enzymes (PCK1 and PCK2), NOX activity and its subunit gp91, ROS, apoptotic cell death, glucose, and lactate, while raising ATP levels." (PMID 35740974, 2022).
cardiac hypertrophy (1 paper, 2021). "Increasing PCK2 promotes hypertrophic growth in mice while knocking down the gene attenuates norepinephrine-induced cardiac hypertrophy." (PMID 35141295, 2021).
colorectal tumors (1 paper, 2025). "PEPCK-M (PCK2) expression has been shown to be significantly increased in pancreatic, lung, and colorectal tumors." (PMID 41142618, 2025).
complication (1 paper, 2024). Any disease or disorder that occurs during the course of, or because of, another disease, treatment, or procedure. "In the tibial artery, genetically predicted increased expression of GSTZ1 and PCK2 was causally linked to an increased risk of peripheral circulatory complications in T2DM patients, while HAGH exhibited an opposite causal effect." (PMID 39280009, 2024).
congenital hypomyelinating neuropathy (1 paper, 2022). "And the other 4 genes have been associated with schizophrenia (MGAT4A), Leigh syndrome (ADI1, OMIM: 256,000), congenital hypomyelinating neuropathy (PLEKHA1, OMIM: 605,253), and ID (PCK2), respectively." (PMID 36320054, 2022).
diffuse large B-cell lymphoma (1 paper, 2026). "In diffuse large B-cell lymphoma, their functional analysis revealed that silencing PCK2 inhibited cell proliferation and induced apoptosis under low-glucose conditions." (PMID 41596441, 2026).
Dravet syndrome (1 paper, 2021). "This study builds on our previous work that demonstrated metabolic deficits and down-regulation of key gluconeogenic genes, pck1 and pck2 in scn1lab mutants, a translatable zebrafish model of Dravet syndrome." (PMID 33842883, 2021). "We utilized a translatable zebrafish model of Dravet syndrome (scn1lab) which exhibits key characteristics of patients with Dravet syndrome and shows metabolic deficits accompanied by down-regulation of gluconeogenesis genes, pck1 and pck2." (PMID 33842883, 2021). "Predictably, oxaloacetate, which is known to increase flux through PEPCK and stiripentol, an antiepileptic drug used in Dravet syndrome patients did not up-regulate either pck1 or pck2." (PMID 33842883, 2021).
gastric cancer (1 paper, 2018). A primary or metastatic malignant neoplasm involving the stomach. "The ATF4-modulated genes, xCT (a cystine/glutamate anti-transporter), tribbles-related protein 3 (TRB3), heme oxygenase 1 (HO-1), and phosphoenolpyruvate carboxykinase 2 (PCK2), were associated with a poorer prognosis for gastric cancer patients." (PMID 30380689, 2018). "In addition, we found that patients with higher TRB3, HO-1, PCK2, and xCT expression in gastric cancer under adjuvant chemotherapy treatment have lower PFS and lower OS than patients with lower TRB3, HO-1, PCK2, and xCT expression, respectively." (PMID 30380689, 2018). "Moreover, higher expression levels of ATF4 and its downstream genes TRB3, HO-1, PCK2, and xCT in gastric cancers were significantly correlated with poorer prognosis for patients receiving chemotherapy." (PMID 30380689, 2018). "Therefore, PCK2 is not involved in the ISR-mediated cisplatin resistance in gastric cancers and NADPH may not be a major contributor to cisplatin resistance in our model." (PMID 30380689, 2018).
laryngeal carcinoma (1 paper, 2022). Carcinoma that arises from the laryngeal epithelium. "For example, Hu reported that PCK2 down-regulation inhibited the invasion, migration, and proliferation of laryngeal cancer under hypoxia, and therefore could be used as a new strategy for laryngeal cancer therapy." (PMID 35804447, 2022).
laryngeal squamous cell carcinoma (1 paper, 2022). A squamous cell carcinoma that arises from the larynx. "There is a positive correlation between the expression of GLUT-1 and PCK2 in laryngeal squamous cell carcinoma." (PMID 35681299, 2022).
lymphoma (1 paper, 2025). A malignant (clonal) proliferation of B- lymphocytes or T- lymphocytes which involves the lymph nodes, bone marrow and/or extranodal sites. "We then investigated the expression of PCK2 among multiple cancer cell lines and discovered significantly higher levels in lymphoma cell lines." (PMID 40182032, 2025).
male impotence (1 paper, 2020). "Thus the YFP tag on pck-2-expressed PEPCK does not obviously accelerate male impotence." (PMID 32240955, 2020).
nasopharyngeal carcinoma (1 paper, 2024). A carcinoma arising from the nasopharyngeal epithelium. "More notably, we verified the effects of PCK2-pACSL4(T679) in in vivo tumor models and clarified its clinical relevance in nasopharyngeal carcinoma (NPC) chemotherapy and radiotherapy cohorts." (PMID 38720107, 2024). "Notably, in addition to confirming the role of PCK2-pACSL4(T679) in multiple preclinical models, we discovered that higher PCK2 and pACSL4(T679) levels are correlated with better response to chemotherapy and radiotherapy as well as lower distant metastasis in nasopharyngeal carcinoma cohorts." (PMID 38720107, 2024).
osteoporosis (1 paper, 2022). A condition of reduced bone mass, with decreased cortical thickness and a decrease in the number and size of the trabeculae of cancellous bone (but normal chemical composition), resulting in increased fracture incidence. "We found that deletion of Pck2 in osteoblasts led to various pathological manifestations, such as craniofacial dysplasia, osteoporosis of long bone (bone loss and increased accumulation of marrow adipocytes)." (PMID 36376276, 2022).
osteosarcoma (1 paper, 2021). A usually aggressive malignant bone-forming mesenchymal neoplasm, predominantly affecting adolescents and young adults. "Low expression of PCK2 has been observed in osteosarcoma patients with metastasis and recurrence, and is associated with poorer survival." (PMID 33903282, 2021).
prostate tumors (1 paper, 2017). "Our findings suggest that PCK2 is critical for the metabolic switch in tumor initiation, and that PCK2 is a potential therapeutic target for aggressive prostate tumors." (PMID 29137367, 2017). "Thus, PCK2 is a potential therapeutic target for aggressive prostate tumors." (PMID 29137367, 2017).
Sepsis (1 paper, 2025). Sepsis is defined as life-threatening organ dysfunction caused by a dysregulated host response to infection. "Our team found that the expression levels of ACADVL, AFG3L2, ETFB, PCCB, and PCK2 were significantly overexpressed in ARDS samples compared to sepsis samples (all P value < .05), which was consistent with the results of bioinformatics analysis." (PMID 40068062, 2025).
Stroke (1 paper, 2023). Sudden impairment of blood flow to a part of the brain due to occlusion or rupture of an artery to the brain. "PostE largely reduced the high expressions of PCK‐1 (***p < .001 at 1 day, *p < .05 at 3 days) as well as PCK‐2 (***p < .001 at 1 and 3 days) after stroke." (PMID 36448290, 2023).
Wilms tumor (1 paper, 2021). An embryonal neoplasm characterized by the presence of epithelial, mesenchymal, and blastema components. "For Family 2 (Wilms tumor), the top-five ranked genes were FAM8A1, TRPM3, PAH, PCK1, and PCK2." (PMID 34624066, 2021).